SNORA2C (small nucleolar RNA, H/ACA box 2C)
Synonyms: ACA34; SNORA34
Gene: Small nucleolar RNA gene on chromosome 12 (48,654,382 to 48,654,518, reverse strand). Ensembl gene ENSG00000221491.
Gene Ontology:
Biological process: RNA processing
Cellular component: nucleolus
Homologues: Orthologues: chimpanzee SNORA2C (99% identical), macaque SNORA2C (96% identical), dog SNORA2C (88% identical), rat LOC120093424 (88% identical), guinea pig SNORA2C (87% identical), rat LOC120102015 (87% identical), rat LOC120097587 (86% identical), rat LOC120098684 (86% identical), pig SNORA2C (85% identical), rabbit SNORA2C (85% identical), rat LOC120102639 (85% identical), rat LOC120095421 (82% identical), and 5 more. Paralogues in human: SNORA2B (74% identical), SNORA2A (72% identical).
Diseases named in the same sentence as SNORA2C in open-access papers:
SNORA2C is named in the same sentence as 2 diseases in open-access papers, as found by Europe PMC text mining. Sharing a sentence is not in itself a finding about the gene and the disease.
SNORA2C shares sentences with these, for which no sentence is quoted: Arthritis (1 paper); pancreatic carcinoma (1).